ADHFE1 (alcohol dehydrogenase iron containing 1)
Description:
Catalyzes the cofactor-independent reversible oxidation of gamma-hydroxybutyrate (GHB) to succinic semialdehyde (SSA) coupled to reduction of 2-ketoglutarate (2-KG) to D-2-hydroxyglutarate (D-2-HG). D,L-3-hydroxyisobutyrate and L-3-hydroxybutyrate (L-3-OHB) are also substrates for HOT with 10-fold lower activities.
Synonyms: HOT; HMFT2263; FLJ32430; ADH8
Tractability: PROTAC: its protein half-life has been measured.
Target class: Enzyme; Oxidoreductase
Gene: Protein-coding gene on chromosome 8 (66,432,467 to 66,468,907, forward strand). Ensembl gene ENSG00000147576.
Subcellular location: Mitochondrion
Subcellular location (Human Protein Atlas): Vesicles
Pathways (Reactome):
Metabolism: Interconversion of 2-oxoglutarate and 2-hydroxyglutarate
Gene Ontology:
Molecular function: hydroxyacid-oxoacid transhydrogenase activity; alcohol dehydrogenase (NAD+) activity; metal ion binding; oxidoreductase activity
Biological process: ketone body catabolic process; 2-oxoglutarate metabolic process
Cellular component: mitochondrion; mitochondrial matrix
Genetic constraint (gnomAD): Loss-of-function variants: 33 observed, 45.66 expected, observed/expected ratio (o/e) 0.72, 90% interval 0.55 to 0.97. The upper end of that interval is the gene's LOEUF score, 0.97, which puts it in group 4 of 6, group 1 being the genes least tolerant of losing a copy. Missense variants: 555 observed, 553.3 expected, observed/expected ratio (o/e) 1, 90% interval 0.94 to 1.08. Synonymous variants: 190 observed, 215.79 expected, observed/expected ratio (o/e) 0.88, 90% interval 0.78 to 0.99.
Homologues: Orthologues: chimpanzee ADHFE1 (99% identical), macaque ADHFE1 (97% identical), dog ADHFE1 (90% identical), rat Adhfe1 (90% identical), guinea pig ADHFE1 (89% identical), mouse Adhfe1 (89% identical), pig ADHFE1 (88% identical), tropical clawed frog adhfe1 (78% identical), zebrafish adhfe1 (72% identical), rabbit ADHFE1 (72% identical), Drosophila melanogaster T3dh (57% identical), Caenorhabditis elegans hphd-1 (47% identical).
Diseases named in the same sentence as ADHFE1 in open-access papers:
ADHFE1 is named in the same sentence as 35 diseases in open-access papers, as found by Europe PMC text mining. Sharing a sentence is not in itself a finding about the gene and the disease. The quoted sentences say what the papers report.
colorectal cancer (9 papers, 2013 to 2023). A primary or metastatic malignant neoplasm that affects the colon or rectum. "The hypermethylation of ADHFE1 has recently been reported to be associated with colorectal cancer differentiation." (PMID 29169318, 2017). "The hypermethylation of Alcohol dehydrogenase iron containing 1 (ADHFE1) was recently reported to be associated with colorectal cancer (CRC) differentiation." (PMID 24886599, 2014). "Up-regulation of ADHFE1 suppressed the proliferation of colorectal cancer cells through regulation of the cell cycle." (PMID 36969015, 2023). "It was reported that in colorectal cancer (CRC), ADHFE1 was hypermethylated, and a high expression level of ADHFE1 was positively associated with tumor differentiation, indicating its tumor-suppressing function in CRC." (PMID 34179501, 2021). "AOC4P is a lncRNA involved in hepatocellular carcinoma and colorectal cancer and ADHFE1 is a breast cancer oncogene." (PMID 33892787, 2021). "Another relatively independent work was based on the precious finding in LGA, in which we found ADHFE1 is a potential early diagnosis biomarker of colorectal carcinoma and adenoma." (PMID 32317010, 2020). "ADHFE1 promoter hyper-methylation was found in colorectal cancer (CRC) and the alcohol could down-regulate the expression of ADHFE1 through hyper-methylation and further induce the proliferation of CRC cells." (PMID 30233644, 2018). "Specifically, in colorectal cancer, EYA4 and ADHFE1 have already been validated as hypermethylated and down-regulated genes." (PMID 37628872, 2023).
adenoma (8 papers, 2013 to 2025). A neoplasm arising from the epithelium. "Comparing with cg10673833, the better discrimination of normal to adenoma and cancer by ADHFE1 raises a great potential for this candidate as a methylation marker to indicate pathological changes." (PMID 32317010, 2020). "Additionally, ADHFE1 methylation at the promoter region has been reported as a potential early diagnostic biomarker with high sensitivity and high specificity in CRC tumor tissues, stool, and adenomas tissues." (PMID 36713578, 2022). "The prevalence of ADHFE1 promoter methylation in CRC and advanced adenoma was higher as compared with adjacent normal colorectal mucosa." (PMID 23517143, 2013). "To examine the methylation status of the ADHFE1 promoter in 124 paired CRC tissue and adjacent normal colorectal mucosa, and 59 independent advanced adenoma tissues, we performed methylation-specific PCR." (PMID 23517143, 2013). "We examined the promoter methylation and mRNA expression of ADHFE1 with 5-aza-2′-deoxycytidine (5-Aza-2-dC) in 12 CRC cell lines, 124 paired CRC and adjacent normal mucosa, and 59 advanced adenomas." (PMID 23517143, 2013). "It was also reported that the ADHFE1 promoter is hypermethylated in CRC and adenoma by another research group." (PMID 23517143, 2013). "The ADHFE1 promoter was hypermethylated in all CRC cell lines, 81.8% in CRCs, and 84.7% in advanced adenomas, with reciprocal change by 5-Aza-2-dC." (PMID 23517143, 2013). "Further analysis indicated that the changes in methylation levels of the four iRFE MDGs, ADHFE1-Cluster1, CNRIP1-Cluster1, MAFB, and TNS4, occurred in adenoma tissues, while changes did not occur until stage IV in cell-free DNA." (PMID 36158666, 2022).
breast carcinoma (7 papers, 2020 to 2025). "Collectively, above data-driven results suggest that DNA methylation are associated with the downregulation of ADHFE1 in breast cancer, and decreased ADHFE1 is a risky factor of patient survival in breast cancer." (PMID 34179501, 2021). "It was recently demonstrated that Myc-induced ADHFE1 forming r-2HG is the main cause of the resulting metabolic reprogramming involving reductive carboxylation glutaminolysis and enhancing mesenchymal transition upon changed epigenetics of breast cancer cells." (PMID 31847543, 2020). "In breast cancer, the amplification of PHGDH and upregulation of ADHFE1 have been implicated in the accumulation of D-2HG." (PMID 39910592, 2025). "The down-regulation of ADHFE1, and GNG7 was associated with poor prognosis in breast cancer patients (p < 0.05)." (PMID 36969015, 2023). "In the Radvanyi Breast dataset, downregulation of ADHFE1 was observed in the breast cancer tissues (fold change = −4.643, P = 2.20 × 10−4)." (PMID 34179501, 2021). "There is a marked difference in ADHFE1 expression among breast cancer cells, although overall expression levels of ADHFE1 are rather low compared to housekeeping genes PPIA and ACTB." (PMID 33916579, 2021). "ADHFE1 has been recognized as a breast cancer oncogene since it is upregulated by Myc via the enhancement of iron metabolism." (PMID 31847543, 2020). "However, ADHFE1 was identified as an MYC-linked oncogene that induces metabolic reprogramming and cellular de-differentiation in breast cancer." (PMID 34179501, 2021). "However, ADHFE1 has been reported to form a mutual regulatory loop with MYC, and ADHFE1 may play an oncogenic role in breast cancer via inducing metabolic reprogramming." (PMID 34179501, 2021). "Therefore, we investigated the frequency of ADHFE1 gene mutation and CNAs in breast invasive carcinoma (BRIC; TCGA Provisional dataset, cBioPortal) to explore whether genetic mechanisms play a role in the downregulation of ADHFE1 in breast cancer." (PMID 34179501, 2021). "Expression of ADHFE1, analyzed using the TCGA and GTEx datasets from GEPIA, was also found to be significantly downregulated in breast cancer compared to the normal breast tissues (P < 0.05)." (PMID 34179501, 2021). "We inquired detailed datasets of breast cancer studies from Oncomine and GEPIA to examine the expression of ADHFE1 in breast cancer tissues and the normal counterparts." (PMID 34179501, 2021). "To estimate ADHFE1 expression (alternatively hydroxyacid-oxoacid transhydrogenase, HOT, EC: 1.1.99.24), we quantified its mRNA levels in breast cancer cells." (PMID 33916579, 2021). "We clearly distinguish the IDH2-dependent and independent production of 2HG in mitochondria and demonstrate the active competition between the 2HG producing machinery in mitochondria, namely ADHFE1 and IDH2 in breast cancer cells in vitro." (PMID 33916579, 2021). "We investigated whether production of mitochondrial 2HG is elevated in breast cancer cell lines and identified active competition for initial substrate, 2OG, between enzymes isocitrate dehydrogenase IDH2 and alcohol dehydrogenase ADHFE1." (PMID 33916579, 2021). "Hence, we evaluated 2HG levels in several breast carcinoma cultured cell lines, derived from primary and secondary tumors and we demonstrated that 2HG is actively formed by IDH2 and ADHFE1 and that there is a competition between these two enzymes, which regulate substrate flux in mitochondria." (PMID 33916579, 2021).
gastric cancer (5 papers, 2021 to 2024). A primary or metastatic malignant neoplasm involving the stomach. "We validated the prognostic value of ADHFE1 in the TCGA-STAD dataset using SurvExpress that patients with gastric cancer in low-risk subgroup had higher expression of ADHFE1 than those in the high-risk subgroup (P = 3.77 × 10−114)." (PMID 34179501, 2021). "High expression of ADHFE1 was positively associated with favorable patient prognosis in breast, colon, and gastric cancers." (PMID 34179501, 2021). "Furthermore, mRNA expression of ADHFE1 was negatively associated with and DNA methylation in gastric cancer tissues (TCGA Provisional, cBioPortal; Pearson r = −0.6530, P < 0.0001)." (PMID 34179501, 2021). "The results obtained from Oncomine and GENT databases suggested that the expression of ADHFE1 is commonly downregulated in cancer tissues, and the expression pattern seems to manifest in cancers including breast, colon, and gastric cancers." (PMID 34179501, 2021). "ADHFE1 mRNA expression was downregulated in gastric cancer tissues compared to the normal counterparts according to both Oncomine and GENT databases." (PMID 34179501, 2021). "Since the expression pattern of ADHFE1 seems to manifest in cancers including breast, colon, and gastric cancers, among others, we chose these three cancer types for subsequent analysis." (PMID 34179501, 2021). "Additionally, we evaluated the prognostic value of ADHFE1 in certain cancer types (breast, colon, and gastric cancers) using several cancer datasets." (PMID 34179501, 2021). "Intriguingly, the expression of ADHFE1 in gastric cancer tissues with a gain of copy number was significantly lower than those with diploid ADHFE1 (P = 0.0001), suggesting alternative regulatory mechanisms potently contribute to transcriptional downregulation of ADHFE1 in gastric cancer." (PMID 34179501, 2021). "Co-expression network analysis of datasets from the GEO database has identified four key genes involved in gastric cancer progression including ITGAX, chemokine (C-C motif) ligand 14 (CCL14), alcohol dehydrogenase iron-containing protein 1 (ADHFE1), and Homeobox B13 (HOXB13)." (PMID 39845786, 2024).
breast tumor (2 papers, 2016 to 2023). "ADHFE1 contributed to metabolic reprogramming with a reductive glutamine metabolism in breast tumors." (PMID 36969015, 2023). "The mRNA expression level of ADHFE1 and GNG7 was significantly down-regulated in the primary breast tumor." (PMID 36969015, 2023).
colon cancer (2 papers, 2017 to 2021). "Significant downregulation of ADHFE1 in patients with colon cancer was observed in the Hong CRC (Oncomine), TCGA-Colon Adenocarcinoma (COAD), and GTEx (GEPIA) datasets (both P < 0.05)." (PMID 34179501, 2021). "On the other hand, an increased methylation level of ADHFE1 was found in colon cancer tissues compared to their normal counterparts (TCGA-COAD, TAGA Wanderer; P < 0.0001)." (PMID 34179501, 2021). "Ethanol treatment promotes the hypermethylation of ADHFE1 and methylation-mediated silencing of ADHFE1, which is responsible for enhanced cell proliferation of colon cancer cells." (PMID 28538665, 2017). "We then investigated whether genetic alterations contributed to the downregulation of ADHFE1 expression in colon cancer." (PMID 34179501, 2021). "ADHFE1 was found to be hypermethylated in CRC tissues and colon cancer cells." (PMID 28538665, 2017). "However, the correlation between ADHFE1 expression and patient survival in colon cancer has not been investigated." (PMID 34179501, 2021).
colorectal adenoma (2 papers, 2020 to 2022). An adenoma that arises from the colon or rectum. "Integration analysis revealed that DNA methylation in the promoter region of ADHFE1 has the most potential for being an early diagnostic biomarker for colorectal adenoma and cancer (sensitivity = 0.96, specificity = 0.95, area under the curve = 0.97)." (PMID 32317010, 2020). "The potential of ADHFE1 as early detection of CRC was also discovered by Fan and his colleagues, whereby they observed hypermethylated ADHFE1 in colorectal adenoma." (PMID 35054365, 2022). "Our results suggest that the DNA methylation of the ADHFE1 promoter is a potential biomarker for distinguishing colorectal adenoma and cancer from normal tissue." (PMID 32317010, 2020).
colorectal tumours (1 paper, 2022). "All probes identified in the promoter region of the ADHFE1 gene were hypermethylated, with cg18065361 exhibiting the highest methylation level in colorectal tumours versus normal tissues." (PMID 35054365, 2022).
esophageal carcinoma (1 paper, 2022). A primary or metastatic malignant neoplasm involving the esophagus. "The methylation of ADHFE1 cg18065361 was also significantly hypermethylated in esophageal carcinoma and head and neck squamous cell carcinoma." (PMID 35054365, 2022).
esophageal squamous cell carcinoma (1 paper, 2022). Esophageal squamous cell carcinoma (ESCC) is a type of esophageal carcinoma (EC) that can affect any part of the esophagus, but is usually located in the upper or middle third. "ADHFE1 acted as a tumour suppressor gene in esophageal squamous cell carcinoma and was reported to be hypermethylated in a Chinese Han population." (PMID 35054365, 2022).
oral cancer (1 paper, 2020). "Taken together, these findings demonstrated that arecoline or NNK exposure could downregulate the miR-30a and miR-379 in oral cancer cells, consequently increase the DNMT3B protein level and recruit DNMT3B binding to ADHFE1 and ALDH1A2 promoter and caused DNA methylation." (PMID 32238162, 2020). "In this study, we found that NNK and arecoline treatment could recruit DNMT3B to ADHFE1 and ALDH1A2 promoter region, subsequently repressed the expression of ADHFE1 and ALDH1A2 in oral cancer." (PMID 32238162, 2020). "Our findings implicate ADHFE1 and ALDH1A2 as tumor suppressor genes in oral cancer and provide rationale for further investigation of retinoids in combination with epigenetic modifiers for the prevention or treatment of oral cancer." (PMID 32238162, 2020). "Ectopic expression of miR-30a and miR-379 could induce re-expression of methylation-silenced ADHFE1 and ALDH1A2, and lead to growth inhibition in oral cancer cells." (PMID 32238162, 2020). "Previously, we found a set of retinoid signaling related genes, including ADHFE1, ALDH1A2, CRBP1, PAX9, GDF10, TGFBR3, and PPARγ were frequently hypermethylated and downregulated in OSCC patient samples, suggesting the severe molecular defects in RA metabolism in oral cancer." (PMID 32238162, 2020).
rectal cancer (1 paper, 2016). A primary or metastatic malignant neoplasm that affects the rectum. "Ten of the 36 (EYA4, FOXI2, CNRIP1, SFRP1, ADHFE1, C2orf40, MAL, PHACTR3, SST, TMEFF2) were known as rectal cancer related genes with aberrant methylation." (PMID 27566576, 2016).
sarcopenia (1 paper, 2024). Progressive decline in muscle mass due to aging which results in decreased functional capacity of muscles. "Consistently across the three outcomes, RXRA, MDM1, RBL2, KCNJ2, and ADHFE1 were identified as risk factors, while NMB, TECPR2, MGAT3, ECHDC2, and GINM1 were identified as protective factors, all with potential as biomarkers for sarcopenia progression." (PMID 39409102, 2024).
Stomach Adenocarcinoma (1 paper, 2021). "From the detailed analysis, decreased expression of ADHFE1 was found in Cui Gastric (Oncomine) and TCGA-Stomach Adenocarcinoma (STAD) and GTEx (GEPIA) datasets (both P < 0.05)." (PMID 34179501, 2021).
tumor (17 papers, 2013 to 2025). "Of 22 differentially methylated promoters common between all LS tumor groups, seven inversely correlated with expression: ADHFE1, DAPP1, FBLIM1, GRIA4, HOXA3, KLF17, and ZNF528." (PMID 40753397, 2025). "Regulated by MYC, ADHFE1 enhances tumor growth and promotes a stem cell-like phenotype, thereby increasing tumor aggressiveness." (PMID 39408832, 2024). "DNMT3B is not only differentially expressed in tumor tissues, but also has significant correlation with ADHFE1 and ALDH1A2 expression." (PMID 32238162, 2020). "However, among these two cancers, CRC showed a significant difference in the methylation level of ADHFE1 between tumours and normal tissues." (PMID 35054365, 2022). "In CRC tissue, ADHFE1 is hyper-methylated in the promoter region corresponding to downregulation of expression that may facilitate tumor growth." (PMID 32317010, 2020). "Alcohol dehydrogenase iron-containing 1 (ADHFE1), an oncogene, induces metabolic reprogramming, promoting both tumor growth and metastasis in BRCA." (PMID 41278297, 2025). "Among the top of the list sorted by the smallest adjusted P values were five genes: ADHFE1, EYA4, FBLIM1, HOXA3, and HOXA5, all hypermethylated in all tumor groups." (PMID 40753397, 2025). "In contrast, the expression level of ADHFE1 and GNG7 was significantly down-regulated in the tumor group." (PMID 36969015, 2023). "Results show that leptin signaling increases the expression of tumor progression and chemoresistance-related genes (ABCB1, WNT4, ADHFE1, TBC1D3, LL22NC03, RDH5, ITGB3) in TNBC cells." (PMID 32471192, 2020). "Moreover, immunohistochemical analysis of the representative specimens of patients with OSCC demonstrated that the expression of ADHFE1 and ALDH1A2 expression was greater in nontumor squamous epithelium than in tumor tissues." (PMID 32238162, 2020).